HCRTR2 (hypocretin receptor 2)
Description:
G protein-coupled receptor that binds neuropeptides orexin-A and orexin-B, two neuropeptides derived from a common precursor, prepro-orexin. Upon neuropeptide ligand binding, HCRTR2 can couple with both G(q)/11 and G(i)/o heterotrimeric G proteins thereby initiating distinct downstream signaling cascades. Involved in regulating the sleep-wake cycle (By similarity). Contributes to central regulation of glucose homeostasis (By similarity).
Synonyms: Ox2R; ORXR2; OXR2
Tractability: Small molecule: an approved drug acts on it; a structure with a bound ligand is known; a high-quality ligand is known; it belongs to a druggable protein family. Antibody: UniProt places it where antibodies can reach, with high confidence; its Gene Ontology location is reachable by antibodies, with high confidence; UniProt predicts a signal peptide or a membrane-spanning region; the Human Protein Atlas places it where antibodies can reach. PROTAC: a small molecule that binds it is known. Other modalities: a drug acting on it is in phase 2 or 3 trials.
Target class: Short peptide receptor (family A GPCR); Family A G protein-coupled receptor; Peptide receptor (family A GPCR); Orexin receptor; Membrane receptor
Chemical probes: DANAVOREXTON (high quality), MK-3697 (high quality), firazorexton (high quality)
Gene: Protein-coding gene on chromosome 6 (55,106,460 to 55,282,617, forward strand). Ensembl gene ENSG00000137252.
Subcellular location: Cell membrane
Subcellular location (Human Protein Atlas): Plasma membrane; Nucleoplasm
Pathways (Reactome):
Signal Transduction: G alpha (q) signalling events; Orexin and neuropeptides FF and QRFP bind to their respective receptors
Gene Ontology:
Molecular function: orexin receptor activity; protein binding; neuropeptide receptor activity; G protein-coupled receptor activity; peptide hormone binding
Biological process: neuropeptide signaling pathway; regulation of cytosolic calcium ion concentration; cellular response to hormone stimulus; chemical synaptic transmission; feeding behavior; glucose homeostasis; regulation of circadian sleep/wake cycle, wakefulness; circadian sleep/wake cycle process; G protein-coupled receptor signaling pathway; locomotion
Cellular component: plasma membrane; membrane; synapse
Genetic constraint (gnomAD): Loss-of-function variants: 15 observed, 38.5 expected, observed/expected ratio (o/e) 0.39, 90% interval 0.26 to 0.6. The upper end of that interval is the gene's LOEUF score, 0.6, which puts it in group 2 of 6, group 1 being the genes least tolerant of losing a copy. Missense variants: 423 observed, 495.42 expected, observed/expected ratio (o/e) 0.85, 90% interval 0.79 to 0.93. Synonymous variants: 207 observed, 188.4 expected, observed/expected ratio (o/e) 1.1, 90% interval 0.98 to 1.23.
Homologues: Orthologues: chimpanzee HCRTR2 (99% identical), macaque HCRTR2 (98% identical), dog HCRTR2 (98% identical), pig HCRTR2 (98% identical), rabbit HCRTR2 (97% identical), mouse Hcrtr2 (94% identical), rat Hcrtr2 (94% identical), guinea pig HCRTR2 (79% identical), zebrafish hcrtr2 (67% identical). Paralogues in human: HCRTR1 (64% identical), NPFFR1 (30% identical), NPFFR2 (28% identical), GALR1 (23% identical), CCKBR (22% identical), CCKAR (22% identical), QRFPR (22% identical), OXTR (20% identical), AVPR1A (19% identical), GALR3 (18% identical), AVPR2 (18% identical), FFAR4 (17% identical), and 4 more.
Diseases named in the same sentence as HCRTR2 in open-access papers:
HCRTR2 is named in the same sentence as 47 diseases in open-access papers, as found by Europe PMC text mining. Sharing a sentence is not in itself a finding about the gene and the disease. The quoted sentences say what the papers report.
narcolepsy (26 papers, 2007 to 2025). A sleep disorder characterized by a tendency for excessive sleepiness during the day which occurs even after adequate sleep in the nighttime. "It was found that dogs inherit narcolepsy (a disorder characterised by increased daytime sleepiness and the inability to control sleep/wake state) through a mutation in the hypocretin (orexin) receptor 2 gene (Hcrtr2)." (PMID 40346938, 2025). "Examples like the famous case of the narcolepsy causing mutation in the canine Hypocretin Receptor 2 gene, which turned the focus of researchers to its human homolog’s role in narcolepsy, have demonstrated how canine genetics can benefit humans." (PMID 31681409, 2019). "HcrtR2-deficient mice show a phenotype similar to narcolepsy, including fragmented wakefulness, while those deficient in HcrtR1 show only mild sleep alterations." (PMID 29928253, 2018). "Although canine HCRTR2 mutations are associated with narcolepsy, mutations in human orexin receptor genes have been associated only with rather moderately elevated disease risks—and, in some cases, the associations have not been met with consensus." (PMID 24834023, 2014). "Narcolepsy is shown in animals such as Deberman/Labrador dogs in which mutation in hypocretin receptor 2 has been determined." (PMID 24644464, 2012). "By using microarray technology we have screened the expression of 29760 genes in the brains of Doberman dogs with a heritable form of narcolepsy (homozygous for the canarc-1 [HCRTR-2-2] mutation), and their unaffected heterozygous siblings." (PMID 17521418, 2007). "Concurrently, naturally occurring canine narcolepsy was traced to mutations in the Hcrtr2 gene." (PMID 41296378, 2025). "For example, a SINEC_Cf insertion in the HCRTR2 gene causes narcolepsy in Doberman pinschers." (PMID 38333557, 2024). "Additional canine data identified a genetic defect in Hcrt receptor 2 (HcrtR2) linked to the development of narcolepsy in dogs, and several studies have confirmed that degenerative loss of Hcrt neurons is responsible for human narcolepsy." (PMID 29928253, 2018). "Their discovery that the etiology of the disorder is a disruption in the hypocretin receptor 2 gene (Hcrtr2) underscores the significance of hypocretins in sleep regulation and paves the way for novel therapeutic strategies for narcolepsy in humans." (PMID 40642209, 2025). "Since mice with Hcrtr2 knockout show increased sleep time and narcolepsy, these data suggest that the effects SB-334867 on sleep are mediated by the Hcrtr2 receptor." (PMID 36411386, 2022). "Accordingly, the dysfunction of this system is linked to narcolepsy, as revealed in dogs with mutated HcrtR2 gene and mice lacking hypocretins or HcrtR2." (PMID 24391536, 2013). "In this study, we re-examined this hypothesis through mass spectrometry (MS) characterization of Pandemrix®, and two other pandemic H1N1 (pH1N1)-2009 vaccines, Arepanrix® and Focetria®, and analyzed anti-HCRTR2 autoantibodies in narcolepsy patients and controls using three independent strategies." (PMID 29220370, 2017). "Nevertheless, the identification of sequence similarity of HCRTR2 and HCRT itself with nucleoprotein (NP) and HA of 2009 H1N1, respectively, strongly suggested a molecular mimicry mechanism in the pathophysiology of narcolepsy." (PMID 35445831, 2022). "Later, additional self-antigens, including the neuropeptide glutamic acid-isoleucine/a-melanocyte-stimulating hormone (NEI/aMSH), the hypocretin receptor 2 (HCRTR2), prostaglandin receptor D2, and neurexin-1-alpha (NRXN1), have been identified as targets of auto-Abs in narcolepsy patients." (PMID 35445831, 2022). "The authors also found anti-HCRTR2 autoantibodies were detectable in post Pandemrix® narcolepsy patients (17 of 20 sera), but not in subjects (0 of 12 sera) after Focetria® vaccination in 2009." (PMID 29220370, 2017). "Anti-HCRTR2 autoantibody is not a significant biological feature of narcolepsy or of post Pandemrix® autoimmune responses." (PMID 29220370, 2017).
narcolepsy (continued). "We also found that previously reported results suggesting molecular mimicry between NP and HCRTR2 could not be reproduced and that autoreactivity by autoantibodies to HCRTR2 was unlikely to play a role in the pathophysiology of narcolepsy." (PMID 29220370, 2017).
Cluster headache (11 papers, 2011 to 2025). A type of headache characterized by repeated attacks of unilateral pain lasting 15 to 180 minutes and associated with local autonomic signs. "Nonetheless, other studies, did not support the association between G1246A polymorphism of the HCRTR2 gene and the risk of cluster headache in diverse populations." (PMID 39560176, 2025). "A recent meta-analysis also failed to support an association between the G1246A polymorphism of the HCRTR2 gene and the overall risk of cluster headache in the population." (PMID 39560176, 2025). "The most studied gene in the susceptibility of cluster headache is HCRTR2 gene that is expressed in the hypothalamus; however, results are not consistent across studies." (PMID 39560176, 2025). "The association between the G1246A polymorphism of the HCRTR2 gene and cluster headache susceptibility has been extensively studied, with mixed results." (PMID 39560176, 2025). "Regarding the HCRTR2 gene, the most studied variant is the rs2653349 SNP, which has been linked primarily to cluster headaches." (PMID 38892431, 2024). "Our research group has previously reported that the 1246G/A polymorphism of the hypocretin receptor 2 (HCRTR2) gene is significantly associated with cluster headache." (PMID 21344296, 2011). "The WGS on four members of the large multigenerational French family of cluster headache found that two family members showing the same phenotypic circadian pattern (familial periodicity) of symptoms had two genetic risk loci in the HCRTR2 and in the CLOCK genes." (PMID 39560176, 2025). "In particular, it was described that the HCRTR1 gene (orexin/hypocretin receptor 1 gene) may be related to migraine and that the 1246G/A polymorphism of the hypocretin receptor 2 (HCRTR2) gene is significantly associated with headache cluster." (PMID 29541053, 2018). "The most studied gene in cluster headache is the HCRTR2, which is expressed in the hypothalamus; however, findings across studies continue to be inconclusive." (PMID 39560176, 2025). "Additionally five intronic polymorphisms, covering more than 75% of the entire 108.35 kb sequence of the HCRTR2 gene, were used to evaluate the association between cluster headache and the OX2/HCRTR2." (PMID 24834023, 2014). "Global Test analysis of the custom hypocretin gene sets, however, failed to reveal evidence for involvement of hypocretin in our RNA-seq data, which is in line with the absence of genetic association of HCRTR2 gene variants with cluster headache in the largest sample studied so far15." (PMID 28074859, 2017).
Obesity (5 papers, 2018 to 2026). Accumulation of substantial excess body fat. "The knockout of BRD2 gene will cause obesity in mouse and HCRTR2 is a kind of orexin receptor, which plays a vital important role in feeding behavior and balance of energy metabolism." (PMID 31024621, 2019). "Due to the limitations of the current model, the role of HCRTR2 in the anti-obesity effects of GLT will be verified in future studies." (PMID 41596924, 2026). "Therefore, the anti-obesity effect of HCRTR2 may be mediated through the regulation of energy metabolism and insulin sensitivity." (PMID 41596924, 2026). "This integrated dysfunction suggests that impaired HCRTR2 signaling in specific neural populations may represent a novel pathway contributing to obesity risk by concurrently disrupting sleep quality and metabolic homeostasis." (PMID 41596924, 2026). "An early study reported that activation of the HCRTR2 pathway could combat diet-induced metabolic dysfunction by increasing energy expenditure and improving leptin sensitivity, positioning it as a potential therapeutic target for obesity and related disorders." (PMID 41596924, 2026). "Findings include missense variants in established drug targets for sleep disorders (HCRTR1, HCRTR2), genes with roles in arousal (TRPC6, PNOC), and genes suggesting an obesity-hypersomnolence pathway (PNOC, PATJ)." (PMID 33568662, 2021). "We identify 123 loci of which 61 replicate in the 23andMe research cohort, including variants in established drug targets for sleep disorders (HCRTR1, HCRTR2), genes with roles in arousal (TRPC6, PNOC), and genes suggesting an obesity-hypersomnolence pathway (PNOC, PATJ)." (PMID 33568662, 2021).
alcohol dependence (2 papers, 2022 to 2025). Physical and psychological dependence on alcohol. "Hcrtr2 encodes for the receptor of neuropeptide hypocretin/orexin, which is known to be dysregulated in alcohol dependence and compulsive alcohol drinking in mice." (PMID 39653249, 2025).
sleep disorder (2 papers, 2021 to 2025). A change from the patient's baseline sleeping pattern, in the hours slept and/or an alteration/dysfunction in the stages of sleep. "“The sleep disorder canine narcolepsy is caused by a mutation in the hypocretin receptor 2 gene,” which has been cited 1,977 times, ranks as the third most influential." (PMID 40642209, 2025).
amyloid (1 paper, 2017). "In rodent models of AD, almorexant, an antagonist that blocks both the OXR1 and OXR2 (HCRTR1 and HCRTR2) orexin receptors, reduces amyloid pathology." (PMID 28993311, 2017).
autosomal dominant polycystic kidney disease (1 paper, 2024). Autosomal dominant form of polycystic kidney disease. "Here, we analyzed orexin-A levels as well as the incidence of SNPs in the hypocretin neuropeptide precursor (HCRT) and its receptors, HCRTR1 and HCRTR2, in 64 patients affected by autosomal dominant polycystic kidney disease (ADPKD) bearing truncating mutations in the PKD1 or PKD2 genes." (PMID 38892431, 2024).
centronuclear myopathy (1 paper, 2017). Centronuclear myopathy (CNM) is an inherited neuromuscular disorder characterized by clinical features of a congenital myopathy and centrally placed nuclei on muscle biopsy. "Insertion of SINEC_Cf elements in the hypocretin receptor-2 and PTPLA genes cause canine narcolepsy in Doberman pinschers and centronuclear myopathy in Labrador retrievers respectively." (PMID 28101368, 2017).
endometrial cancer (1 paper, 2017). Primary or metastatic malignant neoplasm involving the endometrium (mucous membrane that lines the endometrial cavity). "Loss of expression of HCRTR2 correlates with hypermethylation of HCRTR2 in endometrial cancer compared with normal endometrium." (PMID 29100314, 2017).
cancer (3 papers, 2018 to 2023). A tumor composed of atypical neoplastic, often pleomorphic cells that invade other tissues. "Orexins induce high levels of apoptosis, resulting in a massive reduction in cell growth in various cancer cell lines acting at HCRTR1 or HCRTR2." (PMID 29682090, 2018). "In various cancer cell lines, HCRTR2 expression was down-regulated, which may initiate promoter hypermethylation." (PMID 35463319, 2022).
tumor (2 papers, 2022 to 2024). "Orexin activates the orexin receptor HCRTR2, which induces cell apoptosis, indicating that HCRTR2 shares biological characteristics with tumor suppressor genes." (PMID 38586328, 2024). "After orexin receptor HCRTR2 was activated by orexins, apoptosis would be induced, indicating that the HCRTR2 had similar epigenetic characteristics to tumor suppressors." (PMID 35463319, 2022).
HCRTR2 also shares sentences with these, for which no sentence is quoted: insomnia (7 papers); Anxiety (6); Cataplexy (4); Alzheimer disease (3); depression (3); narcolepsy type 1 (3); schizophrenia (3); brain ischemia (2); Hyponatremia (2); migraine (2); neurologic disease (2); Polydipsia (2); attention deficit-hyperactivity disorder (1); brain edema (1); cardiac diseases (1); Cerebral ischemia (1); chronic obstructive pulmonary disease (1); cocaine dependence (1); cognitive disorder (1); delirium (1); dependence (1); edema (1); female infertility (1); gout (1); H1N1 influenza (1); hypersomnia (1); intracerebral hemorrhage (1); ischemia reperfusion injury (1); lymph node metastasis (1); neuralgia (1).
A further 6 diseases each share a sentence with HCRTR2 in 1 paper.